COL7A1 (collagen type VII alpha 1 chain)
Description:
Stratified squamous epithelial basement membrane protein that forms anchoring fibrils which may contribute to epithelial basement membrane organization and adherence by interacting with extracellular matrix (ECM) proteins such as type IV collagen.
Synonyms: EBD1; EBDCT; EBR1; NDNC8
Tractability: Antibody: its Gene Ontology location is reachable by antibodies, with high confidence; UniProt places it where antibodies can reach, with medium confidence; UniProt predicts a signal peptide or a membrane-spanning region.
Target class: Structural protein
Gene: Protein-coding gene on chromosome 3 (48,564,073 to 48,595,329, reverse strand). Ensembl gene ENSG00000114270.
Subcellular location: Secreted, extracellular space, extracellular matrix, basement membrane
Subcellular location (Human Protein Atlas): Endoplasmic reticulum; Vesicles; Predicted to be secreted
Pathways (Reactome):
Extracellular matrix organization: Anchoring fibril formation; Assembly of collagen fibrils and other multimeric structures; Collagen biosynthesis and modifying enzymes; Collagen chain trimerization; Collagen degradation; Fibronectin matrix formation; Integrin cell surface interactions; Laminin interactions
Vesicle-mediated transport: COPII-mediated vesicle transport; Cargo concentration in the ER
Gene Ontology:
Molecular function: extracellular matrix structural constituent conferring tensile strength; protein binding; serine-type endopeptidase inhibitor activity
Biological process: endodermal cell differentiation; cell adhesion; epidermis development; extracellular matrix organization; collagen fibril organization
Cellular component: extracellular matrix; extracellular region; basement membrane; collagen type VII trimer; COPII-coated ER to Golgi transport vesicle; endoplasmic reticulum lumen; endoplasmic reticulum-Golgi intermediate compartment membrane
Genetic constraint (gnomAD): Loss-of-function variants: 297 observed, 473.92 expected, observed/expected ratio (o/e) 0.63, 90% interval 0.57 to 0.69. The upper end of that interval is the gene's LOEUF score, 0.69, which puts it in group 2 of 6, group 1 being the genes least tolerant of losing a copy. Missense variants: 3,441 observed, 4,158.7 expected, observed/expected ratio (o/e) 0.83, 90% interval 0.8 to 0.85. Synonymous variants: 1,464 observed, 1,581.4 expected, observed/expected ratio (o/e) 0.93, 90% interval 0.89 to 0.97.
Gene-disease validity (ClinGen):
ClinGen rates the evidence that COL7A1 causes each of these diseases.
recessive dystrophic epidermolysis bullosa (autosomal recessive): Definitive.
Homologues: Orthologues: chimpanzee COL7A1 (99% identical), rat Col7a1 (83% identical), Caenorhabditis elegans col-99 (8% identical). Paralogues in human: COL4A5 (22% identical), COL4A1 (21% identical), COL4A3 (20% identical), COL4A2 (20% identical), COL4A6 (20% identical), COL5A1 (19% identical), COL11A1 (19% identical), COL11A2 (18% identical), COL4A4 (18% identical), COL5A3 (17% identical), COL5A2 (17% identical), COL2A1 (17% identical), and 25 more.
Diseases named in the same sentence as COL7A1 in open-access papers:
COL7A1 is named in the same sentence as 96 diseases in open-access papers, as found by Europe PMC text mining. Sharing a sentence is not in itself a finding about the gene and the disease. The quoted sentences say what the papers report.
recessive dystrophic epidermolysis bullosa (81 papers, 2006 to 2026). "Recessive dystrophic epidermolysis bullosa (RDEB) is a severe blistering disease caused by COL7A1 pathogenic variants." (PMID 39809737, 2025). "Recessive dystrophic epidermolysis bullosa (RDEB) is a severe genetic disease caused by COL7A1 mutations." (PMID 40362519, 2025). "Recessive dystrophic epidermolysis bullosa (RDEB) is a hereditary dermal blistering disorder caused by mutations in the COL7A1 gene encoding type VII collagen (C7), which progressively results in poor wound healing, fibrosis, and pseudosyndactyly." (PMID 40883988, 2025). "Recessive dystrophic epidermolysis bullosa (RDEB) is caused by mutations in COL7A1, leading to loss or dysfunction of type‐VII collagen (C7), a protein essential for skin stability." (PMID 39853777, 2025). "Pathogenic COL7A1 gene (C7) mutations are the primary cause of recessive dystrophic epidermolysis bullosa (RDEB), and restoring the normal expression of COL7A1 and producing type VII collagen is critical for treating RDEB." (PMID 41376622, 2025). "Recessive dystrophic epidermolysis bullosa is a rare genodermatosis caused by a mutation of the Col7a1 gene." (PMID 38722855, 2024). "Recessive Dystrophic Epidermolysis Bullosa (RDEB) is a rare inherited skin disease caused by variants in the COL7A1 gene, coding for type VII collagen (C7), an important component of anchoring fibrils in the basement membrane of the epidermis." (PMID 37161592, 2023). "Recessive dystrophic epidermolysis bullosa is a debilitating blistering skin disorder caused by loss-of-function mutations in COL7A1, which encodes type VII collagen, the main component of anchoring fibrils at the dermal−epidermal junction." (PMID 37213713, 2023). "For example, iPSCs of patients with recessive dystrophic epidermolysis bullosa (RDEB) caused by nonsense mutations in COL7A1 gene are edited using ABE." (PMID 37340491, 2023). "Recessive dystrophic epidermolysis bullosa (RDEB) is a devastating disease secondary to mutations in the COL7A1 gene that encodes type VII collagen (C7)." (PMID 37809094, 2023). "Recessive dystrophic epidermolysis bullosa (RDEB) is a severe genodermatosis caused by loss-of-function mutations in the COL7A1 gene, which encodes for type VII collagen (C7) protein." (PMID 37213713, 2023). "We previously demonstrated ABE-mediated correction of nonsense mutations in COL7A1 that cause recessive dystrophic epidermolysis bullosa (RDEB) in primary human patient-derived fibroblasts." (PMID 35021064, 2022). "Among them, recessive dystrophic epidermolysis bullosa (RDEB) is a rare genodermatosis characterized by mutations in the COL7A1 gene, which leads to disorders of collagen production and skin fragility, increasing the risk of wounds and scarring." (PMID 35956325, 2022). "Recessive dystrophic epidermolysis bullosa (RDEB) is a rare autosomal inherited skin disorder caused by mutations in the COL7A1 gene that encodes type VII collagen (C7)." (PMID 34884578, 2021). "Recessive dystrophic epidermolysis bullosa is an inherited skin fragility disorder, due to mutations in the COL7A1 gene, resulting in defective anchoring of the epidermis to the dermis." (PMID 34683836, 2021). "Recessive dystrophic epidermolysis bullosa (RDEB) is a rare genetic disease mainly characterized by extreme skin fragility caused by mutations in the COL7A1 gene encoding type VII collagen (C7)." (PMID 33916959, 2021). "Recessive dystrophic epidermolysis bullosa (RDEB) is an incurable disease that causes severe mucocutaneous fragility due to mutations in COL7A1 (encoding type VII collagen [C7])." (PMID 33491668, 2021). "Recessive dystrophic epidermolysis bullosa (RDEB) is a severe skin disease caused by loss-of-function mutations in the COL7A1 gene that encodes type VII collagen (C7)." (PMID 32947957, 2020). "Recessive dystrophic epidermolysis bullosa (RDEB) is a severe skin disease caused by mutation of the COL7A1 gene." (PMID 32947957, 2020).
recessive dystrophic epidermolysis bullosa (continued). "Recessive Dystrophic Epidermolysis Bullosa (RDEB) is an inherited blistering disorder caused by loss-of-function mutations in the COL7A1 gene that codes for type VII collagen (C7)." (PMID 29630593, 2018). "Recessive dystrophic epidermolysis bullosa (RDEB) is caused by a wide variety of mutations in COL7A1-encoding type VII collagen, which is essential for dermal-epidermal adhesion." (PMID 30195791, 2018). "Recessive dystrophic epidermolysis bullosa (RDEB) is a severe disorder caused by mutations to the COL7A1 gene that deactivate production of a structural protein essential for skin integrity." (PMID 28250968, 2016). "Recessive dystrophic epidermolysis bullosa (RDEB) is a monogenic disorder resulting from mutations in the type VII collagen gene (COL7A1) on chromosome 3." (PMID 28250968, 2016). "Recessive dystrophic epidermolysis bullosa (RDEB) is an inherited skin fragility disorder caused by mutations in the COL7A1 gene, which encodes collagen VII (C7), an extracellular matrix (ECM) adhesion protein." (PMID 26194911, 2015). "We previously reported generation of keratinocytes from human iPSCs for use in the treatment of recessive dystrophic epidermolysis bullosa (RDEB) caused by mutations in the COL7A1 gene." (PMID 24147053, 2013). "Recessive Dystrophic Epidermolysis Bullosa (RDEB) is a genodermatosis caused by more than 500 different mutations in the COL7A1 gene and characterized by blistering of the skin following a minimal friction or mechanical trauma." (PMID 20920254, 2010). "Recessive dystrophic epidermolysis bullosa (RDEB) is a severe blistering condition caused by pathogenic variants in the COL7A1 gene and may present with different disease endotypes." (PMID 39809737, 2025). "Recessive dystrophic epidermolysis bullosa (RDEB) is an inherited blistering disorder caused by mutations in the COL7A1 gene encoding type VII collagen, the major component of anchoring fibrils at the basement membrane zone (BMZ) at the epidermal-dermal junction of the skin." (PMID 24147053, 2013). "Recessive dystrophic epidermolysis bullosa (RDEB) is a rare and severe mucocutaneous fragility disorder due to mutations in the COL7A1 gene encoding collagen VII, the major constituent of anchoring fibrils essential for epithelial adhesion." (PMID 40091088, 2025). "Recessive dystrophic epidermolysis bullosa (RDEB) is an orphan genetic disease caused by mutations in COL7A1, leading to skin and mucosal blisters and erosions upon minor trauma." (PMID 39001538, 2024). "Functional gene delivery has been successfully applied in several clinical studies for genetic diseases, such as recessive dystrophic epidermolysis bullosa (RDEB), a rare condition caused by mutations in the COL7A1 gene." (PMID 40625571, 2023). "PEs have also been utilized to correct COL7A1 mutations in recessive dystrophic epidermolysis bullosa (RDEB) patient-derived fibroblasts, and functional rescue was observed." (PMID 37051232, 2023). "Recessive dystrophic epidermolysis bullosa (RDEB), a skin-blistering disease secondary to COL7A1 mutations and associated with chronic wounding, inflammation, fibrosis, and cutaneous squamous cell carcinoma (cSCC), models this dynamic." (PMID 37809094, 2023). "Recessive dystrophic epidermolysis bullosa (RDEB) is a rare, devastating blistering genodermatosis caused by mutations in the COL7A1 gene, which encodes for type VII collagen and is necessary for dermal-epidermal adhesion and integrity." (PMID 36253825, 2022). "Mutations in COL7A1 cause the severe inherited blistering disorder recessive dystrophic epidermolysis bullosa (RDEB) affecting skin and mucosae, associated with a greatly increased risk of skin cancer." (PMID 35320498, 2022). "Recessive dystrophic epidermolysis bullosa (RDEB) is a rare, debilitating autosomal recessive disease caused by biallelic mutations in COL7A1, the gene encoding type VII collagen (C7)." (PMID 36253825, 2022).
recessive dystrophic epidermolysis bullosa (continued). "A paradigmatic disorder in this context is recessive dystrophic epidermolysis bullosa (RDEB), a rare genetic skin blistering disease caused by mutations in COL7A1 encoding collagen VII." (PMID 34459121, 2021). "The most severe form of EB is recessive dystrophic epidermolysis bullosa (RDEB), attributed to mutations in the COL7A1 gene, that encodes the skin structural protein type VII collagen (C7)." (PMID 34884578, 2021). "Recessive dystrophic epidermolysis bullosa (RDEB) is a prototypical recessive condition and is characterized by mutations to the COL7A1 gene on chromosome 3." (PMID 29565806, 2018). "We discovered a novel pathological COL7A1 variant that results in a premature stop codon and subsequently causes recessive dystrophic epidermolysis bullosa (RDEB) in the CAS breed." (PMID 28493971, 2017). "Recessive dystrophic epidermolysis bullosa (RDEB) is a debilitating genodermatosis caused by loss-of-function mutations in COL7A1." (PMID 26763448, 2016). "In 2000, Dr. Gau-Tyan Lin had identified a homozygous intronic splice-site mutation at the +1 position of intron 5 (682+1G→A) of COL7A1 in the family of this patient with recessive dystrophic epidermolysis bullosa (RDEB)." (PMID 16480504, 2006). "Several local gene therapies have been developed using modified herpes simplex virus 1 (HSV-1) vector carrying wild-type genes, such as COL7A1 for recessive dystrophic epidermolysis bullosa or TGM1 for autosomal recessive congenital ichthyosis." (PMID 41155269, 2025). "Type VII collagen (COL7) can be encoded by COL7A1, and its mutations may cause recessive dystrophic epidermolysis bullosa (RDEB) that is a severe skin fragility disease." (PMID 40143206, 2025). "Recessive dystrophic epidermolysis bullosa (RDEB) and junctional epidermolysis bullosa (JEB) are severe blistering skin disorders caused by mutations in genes encoding type VII collagen (COL7A1) and laminin 332 (LAMA3, LAMB3, or LAMC2), respectively." (PMID 41210582, 2025). "Indeed, amlexanox showed readthrough activity in human cells harboring PTC mutation in COL7A1, from patients with recessive dystrophic epidermolysis bullosa (RDEB)." (PMID 38543100, 2024). "In 2023, the US FDA approved Beremagene Geperpavec for the treatment of recessive dystrophic epidermolysis bullosa (RDEB), a monogenic disease caused by mutations in COL7A1." (PMID 38928229, 2024). "Amlexanox was also shown to induce readthrough of the COL7A1 gene in patients with recessive dystrophic epidermolysis bullosa (RDEB)." (PMID 36979640, 2023). "Thus, patients with the highly disabling genodermatosis, the recessive dystrophic epidermolysis bullosa (RDEB), carry mutations in the COL7A1 gene encoding for type seven collagen, the main component of anchoring fibrils supporting cell binding to the BM." (PMID 35572966, 2022). "Base editing introduces precise single-nucleotide edits in genomic DNA and has the potential to treat genetic diseases such as the blistering skin disease recessive dystrophic epidermolysis bullosa (RDEB), which is characterized by mutations in the COL7A1 gene and type VII collagen (C7) deficiency." (PMID 36385635, 2022). "Recessive dystrophic epidermolysis bullosa (RDEB) is a lifelong genodermatosis associated with blistering, wounding, and scarring caused by mutations in COL7A1, the gene encoding the anchoring fibril component, collagen VII (C7)." (PMID 35347281, 2022). "Petrova and colleagues designed a genetically modified MSC for expressing collagen type VII alpha 1 chain (COL7A1) for the treatment of recessive dystrophic epidermolysis bullosa (RDEB)." (PMID 35189962, 2022). "COL7A1 mutation causes recessive dystrophic epidermolysis bullosa (RDEB)." (PMID 34553848, 2021). "Recessive dystrophic epidermolysis bullosa (RDEB) is an inherited blistering skin disease, resulting from biallelic mutations in COL7A1, the gene encoding type VII collagen (C7)." (PMID 34515407, 2021).
recessive dystrophic epidermolysis bullosa (continued). "Progress have been also done in studying the recessive dystrophic epidermolysis bullosa (RDEB, OMIM #226600), a severe inherited skin disorder caused by mutations in COL7A1 gene." (PMID 32591003, 2020). "However, in recessive dystrophic epidermolysis bullosa (RDEB), a severe genetic disorder caused by mutations in the COL7A1 gene, which encodes type VII collagen (C7), these processes are profoundly disrupted." (PMID 40362519, 2025). "Recessive dystrophic epidermolysis bullosa (RDEB) is an autosomal monogenic skin disease caused by mutations in COL7A1 gene and lack of functional type VII collagen (C7)." (PMID 38027067, 2023). "More importantly, HPAEs could efficiently deliver COL7A1 plasmids to restore high-level collagen VII (C7) expression in recessive dystrophic epidermolysis bullosa (RDEB) knockout and grafting mouse models." (PMID 37898777, 2023). "These same genes, under an autosomal recessive inheritance transmission are responsible for various forms of epidermolysis bullosa (EB: Non-Herlitz junctional epidermolysis bullosa (nH-JEB) COL17A1; recessive dystrophic epidermolysis bullosa (RDEB) COL7A1; junctional EB (JEB) LAMA3, LAMB3, LAMC2)." (PMID 37228816, 2023). "We present a homozygous missense mutation in the COL7A1 gene (NM_000094.4: c.6262G>A, p.G2088R) in a case of inversa recessive dystrophic epidermolysis bullosa (RDEB-I) from a nonconsanguineous Vietnamese family." (PMID 35581191, 2022). "Finally, there were cutaneous squamous cell carcinomas from patients with recessive dystrophic epidermolysis bullosa (RDEB), a rare hereditary disorder characterized by chronic blistering in the skin and caused by germline mutations in collagen VII (COL7A1)." (PMID 34272401, 2021). "Recessive dystrophic epidermolysis bullosa (RDEB) is caused by mutations in COL7A1 resulting in reduced or absent type VII collagen, aberrant anchoring fibril formation and subsequent dermal-epidermal fragility." (PMID 26380979, 2015). "Recessive dystrophic epidermolysis bullosa (RDEB) is one of the most severe nonsyndromic forms, which is caused by biallelic loss‐of‐function variants in the collagen type VII gene (COL7A1, OMIM accession number: 120,120)." (PMID 32537942, 2020). "The self-inactivating COL7A1 retrovirus vector expressing type VII collagen was applied for the transduction of fibroblasts from recessive dystrophic epidermolysis bullosa (RDEB) patients." (PMID 30832256, 2019). "DEB can be either dominant or recessive (then called recessive dystrophic epidermolysis bullosa or RDEB), with mutations in gene coding for collagen type VII (COL7A1) that localizes to the anchoring fibrils, structures that ensure the adhesion of the basal lamina with the extracellular matrix." (PMID 25724199, 2015).